METTL3 (methyltransferase 3, N6-adenosine-methyltransferase complex catalytic subunit)
Diseases named in the same sentence as METTL3 in open-access papers (continued):
Sharing a sentence is not in itself a finding about the gene and the disease.
liver cancer (continued). "To evaluate whether the global m6A level is related to tumorigenesis in liver cancer, we generated a series of various expression levels of METTL3 in the normal liver cell line WRL68." (PMID 32368828, 2020). "Moreover, after Mettl3 knockdown in liver cancer cells, Western blot analysis validated that Mettl3 knockdown decreased the protein level of Snail, MMP2, MMP9, and FN1, but increased that of E-Cad, in both HepG2 and MHCC97H cells." (PMID 32483411, 2020). "Thus, to explore the regulatory role of mitogen-responsive SUMOylation of Mettl3 and its relation to liver cancer metastatic potential, MHCC97H and HEP3B cells with high and low metastatic potential 33, 34, respectively, were compared." (PMID 32483411, 2020). "As reported in previous research, METTL3 promotes liver cancer progression through YTHDF2." (PMID 31824761, 2019). "Liver‐specific knockout of N6‐methyladenosine (m6A) methyltransferase METTL3 significantly accelerated hepatic tumor initiation under various oncogenic challenges, contrary to the previously reported oncogenic role of METTL3 in liver cancer cell lines or xenograft models." (PMID 40103332, 2025). "Thus, targeting the METTL3-YTHDF1-BFSP1 axis may be a potential strategy for liver cancer treatment." (PMID 40097750, 2025). "Therefore, we then focussed on examining the effect and mechanism of METTL3 in liver cancer." (PMID 35348293, 2022). "However, it remains to be elucidated whether Mettl3 could epigenetically promote oncogenes in liver cancer through its self-regulatory properties." (PMID 32483411, 2020). "Therefore, we hypothesized that upregulation of Mettl3 SUMOylation in response to mitogen stimulation in liver cancer might be due to UBC9 upregulation." (PMID 32483411, 2020). "Moreover, the precipitated protein complexes included more SUMOylated Mettl3-Flag in liver cancer cells expressing Mettl3-Flag, SUMO1, and scramble siRNA than in cells expressing Mettl3-Flag, SUMO1, and Ubc9 siRNA, indicating that UBC9 is required for Mettl3 SUMOylation." (PMID 32483411, 2020). "METTL3/METTL14 can enhance the expression of ACLY and SCD1 through m6A modification, thereby activating lipid synthesis and accumulation in liver cancer cells." (PMID 41522342, 2026). "First, although we have confirmed the role of METTL3/BFSP1/TMOD4 axis in the progression and metastasis of liver cancer, since this study is only verified in cell and liver cancer xenograft models, other animal models are needed for further verification." (PMID 40097750, 2025). "METTL3 can also catalyze YTHDF1 mediated m6A to increase Snail mRNA translation and epithelial-mesenchymal transition to induce liver cancer metastasis." (PMID 40097750, 2025). "Here, we found that METTL3-mediated BFSP1 mRNA m6A modification enhances BFSP1 stability and promotes aerobic glycolysis and invasion of liver cancer cells." (PMID 40097750, 2025). "In liver cancer, METTL3 promotes the expression of SOCS2 through YTHDF2 dependent enhancement of SOCS2 m6A modification, which in turn induces lung metastasis of liver cancer." (PMID 40097750, 2025). "In summary, METTL3 mediated m6A modification of BFSP1 mRNA induced the viability and invasion of liver cancer cells by activating aerobic glycolysis." (PMID 40097750, 2025). "It has also been confirmed that METTL3-mediated m6A-IGF2BP3-dependent modification upregulates LARP4B expression, thereby promoting liver cancer progression and metastasis." (PMID 40097750, 2025). "METTL3 knockdown inhibited the expression of BFSP1 mRNA and the m6A level of total RNA in liver cancer cells." (PMID 40097750, 2025). "Combined upregulation of METTL3 and YTHDF1 was validated as a biological marker reflecting the malignancy level of liver cancer and patient prognosis." (PMID 38856795, 2024). "Experimentally, METTL3 acts synergistically with YTHDF2 to inhibit the expression of SOCS2, encouraging liver cancer (HCC) development and progression." (PMID 37675218, 2023).
liver cancer (continued). "Liver cancer cell lines, including HepG2, Huh7, Hep3B, PLC/PRF5, and BEL7404, also exhibited elevated METTL3 expression compared to the immortalized normal hepatocellular cells HepaRG." (PMID 38012755, 2023). "Further, in human liver cancer cell line MHCC97H, it was also found that METTL3 is SUMOylated by Ubc9, and increase in SUMOylation of METTL3 correlated with Ubc9 up-regulation." (PMID 35725909, 2022). "In liver cancer, enhancing LINC00958 stability via METTL3 through m6A modification leads to its upregulation, thereby promoting cancer progression." (PMID 36581942, 2022). "However, whether the effect of miR‐589‐5p on liver cancer was associated with the METTL3‐mediated m6A methylation has not been researched." (PMID 35348293, 2022). "In conjunction with METTL3-mediated m6A modification, YTHDF1 can directly induce the translation of Snail, a key transcription factor of EMT, thereby promoting liver cancer metastases." (PMID 35884552, 2022). "For example, in liver cancer, enhancing LINC00958 stability via METTL3 m6A modification results to its upregulation, which thereby promotes cancer progression." (PMID 36581942, 2022). "The knockdown of METTL3 or YTHDF1 attenuated Snail expression and suppressed liver cancer migration and invasion." (PMID 36009465, 2022). "However, whether m6A modification in liver cancer was mediated by METTL3 remained unknown." (PMID 35348293, 2022). "Analysis of clinical samples further showed that the levels of METTL3 and FOXO3 expression are closely related in patients with liver cancer are closely related." (PMID 34246319, 2021). "Further, SUMOylation of Mettl3 was increased upon mitogen stimulation, which correlated with UBC9 upregulation, and was positively correlated with high metastatic potential of liver cancer." (PMID 32483411, 2020). "For example, in liver cancer, YTHDF1 mediates m6A-increased translation of Snail mRNA, and the methylation is catalyzed by METTL3, suggesting the acceleration mediated by METTL3/YTHDF1 complex for the methylated target mRNA30." (PMID 33099572, 2020). "Studies have reported an opposing trend in the expression of METTL3 and METTL14 in patients with liver cancer." (PMID 32307908, 2020). "By contrast, depletion of UBC9 impeded SUMO-1 conjugation on Mettl3 in liver cancer cells upon mitogen stimulation, suggesting that UBC9 is both necessary and sufficient for mitogen-induced Mettl3 SUMOylation." (PMID 32483411, 2020). "In summary, the combination of METTL3 and YTHDF1 can be used as biomarker to reflect the malignant degree of liver cancer and evaluate its prognosis." (PMID 31810483, 2019). "For example, knockdown of METTL3 in HCC can reduce m6A methylation-mediated degradation of SOC2 and then enhance its expression, thus inhibiting the progression of liver cancer." (PMID 30886897, 2019). "The results showed that overexpression of METTL3 and YTHDF1 promoted the ECAR levels and reduced the OCR levels in liver cancer cells, which could be reversed by knockdown of BFSP1." (PMID 40097750, 2025). "Additionally, METTL3 enhances the stability of BFSP1 mRNA in a YTHDF1 dependent manner, thereby promoting aerobic glycolysis in liver cancer cells." (PMID 40097750, 2025). "In summary, METTL3-mediated m6A methylation of BFSP1 mRNA plays an important role in the aerobic glycolysis and progression of liver cancer, providing a potential therapeutic strategy for liver cancer." (PMID 40097750, 2025). "METTL3 specifically maintains LINC00106 stability by promoting the differentiation of m6A in liver cancer cells, increasing the abundance of LINC00106 in the nucleus, and promoting the stem cell and metastasis characteristics of liver cancer." (PMID 37180577, 2023).
liver cancer (continued). "Among these, YTHDF1 tends to stabilize the transcript and promote mRNA translation, while several studies have demonstrated that METTL3 enhances targeted mRNA stability and translation in a YTHDF1-dependent manner in cervical cancer, oral squamous cell carcinoma and liver cancer." (PMID 34996469, 2022). "Moreover, the methyltransferase METTL3 was discovered to regulate the degradation of SOCS2 mRNA, enhancing the progression of liver cancer in a YTHDF2-mediated m6A-dependent manner." (PMID 34996459, 2022). "The absence of METTL3 under hypoxic conditions promotes the resistance of cultured liver cancer cells to sorafenib, enhances and the expression of angiogenic genes and activates autophagy-related pathways." (PMID 34246319, 2021). "However, the critical m6A writers (METTL3, METTL14) were also reported to serve as tumor suppressor in GBM and liver cancer 19,20." (PMID 32284755, 2020). "On the contrary, Snail knockdown attenuated the facilitating effect of Mettl3 on wound healing via METTL3 overexpression in HCC cells, suggesting that the effect of Mettl3 on the progression of liver cancer cells may depend on Snail expression." (PMID 32483411, 2020). "Overall, our study revealed that METTL3 and IGF2BP2, acting as an oncogene, maintained FEN1 expression through an m6A-IGF2BP2-dependent mechanism in HCC cells, and indicated a potential biomarker panel for prognostic prediction in liver cancer." (PMID 33224879, 2020). "Moreover, mitogen stimulation triggered Mettl3 SUMOylation and enhanced SUMO1 conjugation of Mettl3 through UBC9 upregulation, and this response showed a positive correlation to liver cancer with high metastatic potential." (PMID 32483411, 2020). "Therefore, we speculated that METTL3 may mediate the m6A modification of BFSP1 mRNA and affect aerobic glycolysis in liver cancer by enhancing the stability of BFSP1 mRNA in a YTHDF1 dependent manner." (PMID 40097750, 2025). "Moreover, upregulated METTL3 and YTHDF1 expression was found in liver cancer that could serve as adverse prognosis factors for patients." (PMID 36009465, 2022). "Moreover, we have demonstrated that linear MEG3 inhibits METTL3 through blocking HULC in human liver cancer (data not shown)." (PMID 33425489, 2021). "Moreover, we have clearly demonstrated that MEG3 inhibits METTL3 through blocking HULC in human liver cancer (data not shown)." (PMID 33425489, 2021). "Transient transfection with Mettl3-WT, but not Mettl3-KR, promoted cell growth/proliferation, epithelial-mesenchymal transition (EMT), and viability, while decreasing apoptosis in liver cancer, indicating that Mettl3 SUMOylation is essential for its oncogenic properties." (PMID 32483411, 2020). "Therefore, our results demonstrate that, unlike its role in established HCC, METTL3 has a tumor‐inhibitory effect on the occurrence of HCC in the early stages of its development, suggesting that future liver cancer treatments targeting METTL3 should consider the stage of tumor progression." (PMID 40103332, 2025).
leukemia (93 papers, 2018 to 2026). A malignant (clonal) hematologic disorder, involving hematopoietic stem cells and characterized by the presence of primitive or atypical myeloid or lymphoid cells in the bone marrow and the blood. "In immune-deficient mouse models, downregulation of METTL3 expression leads to cell cycle arrest, blockade of leukemia cell differentiation, and inhibition of leukemia formation." (PMID 39473440, 2024). "Loss of METTL3 in human myeloid leukemia cell lines triggers receptor mouse cell differentiation and apoptosis, thereby slowing down the progression of leukemia." (PMID 39473440, 2024). "For the functional study, we found that overexpression of RNF113A significantly inhibited AML cell proliferation, enhanced drug sensitivity, and effectively alleviated the leukemia-promoting effects caused by METTL3 overexpression in vitro." (PMID 37280654, 2023). "METTL3 deficiency led to cell cycle arrest, leukemic cell differentiation, and the inability to initiate leukemia in immunodeficient mice." (PMID 36307883, 2022). "This inhibitor not only significantly inhibits the growth, differentiation and apoptosis of AML caused by METTL3 but also selectively decreases the m6A level of leukemia-related mRNA; the decrease in its expression is consistent with translation defects." (PMID 34778277, 2021). "There was an article to explain the effect of METTL3 on WTAP, and the upregulation of METTL3 can lead to an increase of the WTAP protein level in leukemia, causing the carcinogenic effect of leukemia." (PMID 33237039, 2020). "In addition, METTL3 loss in human myeloid leukemia cell lines can lead to cell differentiation and apoptosis and hinder the progress of leukemia in recipient mice in vivo." (PMID 34745269, 2021). "CEBPZ was identified as a novel recurrently mutated gene in AML, suggesting that in this leukaemia might be lost the co-transcriptional recruitment of METTL3." (PMID 30096915, 2018). "In leukemia, overexpression of METTL3 has been shown to increase MYC pathway activity, supporting leukemic CSCs survival." (PMID 41228380, 2025). "Genetic knockdown of METTL3 in AML cells causes cell-cycle arrest and induces differentiation, and METTL3-deficient leukaemia cells fail to propagate the disease in vivo." (PMID 40651916, 2025). "Preclinical studies, such as the development of the first-in-class METTL3 inhibitor STM2457 in leukemia, have demonstrated that pharmacological disruption of m6A machinery can impair cancer stemness." (PMID 41228380, 2025). "In summary, our study presents an exciting case for the use of selective METTL3 degraders in the context of leukemia." (PMID 40453361, 2024). "METTL3 has been previously reported to sustain leukemia cells in a proliferating and undifferentiated state." (PMID 40453361, 2024). "This cluster comprises 14 keywords, including messenger RNA, N6-methyladenosine, m6A, translation, differentiation, RNA methylation, nuclear RNA, METTL3, tumorigenesis, metabolism, demethylase, leukemia, and messenger RNA." (PMID 39473440, 2024). "In immunodeficient mice, downregulation of METTL3 leads to cell cycle arrest, leukemia cell differentiation, and an inability to establish a leukemia model." (PMID 39445003, 2024). "Studies have found that both mRNA and protein expression levels of METTL3 significantly increase in leukemia cells." (PMID 39473440, 2024). "For instance, inhibiting the activity of the m6A methyltransferase METTL3 reduces m6A levels, thereby suppressing leukemia cell proliferation and survival." (PMID 39445003, 2024). "STM2457 can inhibit the catalytic activity of METTL3 and has been previously shown to affect the proliferation of leukaemia and bile duct tumour cells." (PMID 36932427, 2023). "AML cells exhibit a high level of expression of METTL3, which has been observed to expedite the progression of leukemia in murine models." (PMID 38052820, 2023).
leukemia (continued). "A recently discovered METTL3 inhibitor named STM2457 exerted a significant antitumor effect on leukemia both in vitro and in vivo, providing proof that METTL3 is a potential therapeutic target in antitumor therapy." (PMID 36810108, 2023). "Meanwhile, METTL3 has been found to directly mediate the progression of some diseases, such as leukemia, as suppression of METTL3 results in a selective decrease of m6a levels on leukemogenic mRNAs." (PMID 37069649, 2023). "Our findings have defined an important tumor-suppressive circRNA in AML and provided a potential strategy to induce METTL3 degradation in leukemia treatment." (PMID 37280654, 2023). "The downregulation of METTL3 hindered the maintenance of leukemia, including cell cycle arrest, leukemic cell differentiation, and failure to establish leukemia." (PMID 37065445, 2023). "Emerging evidence revealed that METTL3-induced m6A modification played an important role in acquired resistance to tyrosine kinase inhibitors in leukemia cells, PLX4032 resistance in melanoma, and cisplatin resistance in epithelial ovarian cancer." (PMID 37161388, 2023). "In a mouse model of leukemia, the depletion of METTL3 was shown to induce cell differentiation and apoptosis via the same mechanism to prevent the progression of leukemia in mice." (PMID 35141221, 2022). "Mutation of METTL3 was more frequently observed in BLCA, endometrial carcinoma, melanoma, cervical squamous cell carcinoma, COAD, leukemia, and GBM." (PMID 36614956, 2022). "In leukemia cell lines K562 and kasumi-1, both METTL3 and METTL14 promote cell proliferation and cell cycle, and the knockdown of METTL3 and METTL14 inhibits proliferation, and induces apoptosis and differentiation." (PMID 35154467, 2022). "In the MOLM-13 leukemia cell line, knockdown of Mettl3 increased protein expression of pro-apoptotic proteins CASP3, CASP7, and BIM." (PMID 35350378, 2022). "As METTL3 has been found to serve an oncogenic function in leukemia, the in vitro and in vivo efficacy of STM457 was explored as a therapeutic for AML." (PMID 35350378, 2022). "In leukemia cell lines, knockdown of METTL3 or METTL14 inhibited cell proliferation, induced cell cycle arrest and decreased the ability of the cells to form colonies." (PMID 35154467, 2022). "It was further validated to selectively bind to METTL3 by X-ray crystallography, and it slightly suppresses the expression of METTL3 but significantly reduces m6A levels in the mRNA fraction in the leukemia cell line MOLM-13 and human osteosarcoma U2OS cells." (PMID 35164788, 2022). "Further studies are now warranted to determine the potential therapeutic relevance of METTL3 inhibitors in development to treat leukaemia to benefit patients with PCa." (PMID 36733939, 2022). "Meanwhile, Isaia Barbieri reported that METTL3 is necessary for leukemia cell growth and in maintaining an undifferentiated state." (PMID 35574332, 2022). "In immunodeficient mice, downregulation of METTL3 leads to cell-cycle arrest, leukemia cell differentiation, and leukemia establishment failure." (PMID 34745269, 2021). "The authors found that ‘Mettl3′ is normally expressed in CD34+ hematopoietic stem/progenitor cells (HSPCs) but aberrantly expressed in leukaemia cells as compared to the other tumour-types." (PMID 34207299, 2021). "METTL3 promotes the growth of leukemia cells by inhibiting the differentiation of hematopoietic stem/progenitor cells, while knocking out METTL3 induces cell differentiation and delays the progression of leukemia in recipient mice." (PMID 34858499, 2021). "Researchers have developed the small molecule STM2457, a bioavailable inhibitor of the m6A writer METTL3, to study the enzyme activity after targeting METTL3 in the context of the therapeutic potential of anti-leukemia strategy." (PMID 34794452, 2021).